APOE (apolipoprotein E)
Diseases named in the same sentence as APOE in open-access papers (continued):
Sharing a sentence is not in itself a finding about the gene and the disease.
atherosclerosis (continued). "Our previous work and others have found that protocatechuic acid could inhibit atherosclerosis development and reduce inflammation burden in whole macrophage populations within atherosclerotic plaques in apolipoprotein E-deficient (ApoE−/−) mice." (PMID 40292571, 2025). "Preclinical data from ApoE-deficient mouse models demonstrated that liraglutide improved plaque stability, reduced endothelial dysfunction, and attenuated weight gain in advanced atherosclerosis." (PMID 40803202, 2025). "In addition, this macrophage activation profile is consistent with an increased risk of early atherosclerosis, which is compatible with the finding of early-onset ischemic heart disease in the patients with p.(Leu167del) (APOE-ε3) reported in literature." (PMID 40149441, 2025). "PSRC1 deficiency elevates TMAO and worsens atherosclerosis in ApoE-/- mice through gut dysbiosis." (PMID 40356907, 2025). "For instance, ApoE-deficient mice with haploinsufficient DNA repair enzyme kinase, ataxia telangiectasia mutated, demonstrated greater nuclear DNA damage, and accelerated atherosclerosis progression." (PMID 40700116, 2025). "Furthermore, endothelial deficiency of IGF-1 receptor (IGF1R) caused endothelial barrier dysfunction and promoted atherosclerosis in ApoE-deficient mice." (PMID 40478326, 2025). "In a study conducted in apolipoprotein E-deficient mice, butyrate limited cholesterol uptake in a dose-dependent manner with less atherosclerotic lesions, suggesting that butyrate protects from diet-induced atherosclerosis." (PMID 39772703, 2025). "The APOE genotypes, including three alleles (e2, e3, and e4), exert a distinct impact on lipids and inflammation and could be associated with atherosclerosis and hypertension." (PMID 40429697, 2025). "From a pathophysiological perspective, animal experiments demonstrated that excess phosphate intake decreased atherosclerosis formation partly by changing the profile of peripheral monocytes or inducing apoptosis of macrophages in apolipoprotein E-deficient mice." (PMID 40386020, 2025). "Furthermore, the application of PCL in ApoE−/− mice led to the discovery that regions where flow was disturbed were significantly more susceptible to the development of atherosclerosis." (PMID 40072106, 2025). "The only two studies that examined gammaherpesvirus-ApoE interactions demonstrated that murine gammaherpesvirus 68 (MHV68) infection accelerates the development of atherosclerosis in ApoE-deficient mice infected at weaning with a high dose of MHV68 (5 × 105 PFU)." (PMID 40439406, 2025). "Indeed, transgenic overexpression of ADAMTS1 caused inflammatory cell infiltration into extracellular spaces and severe remodeling after carotid artery ligation in ApoE-deficient atherosclerosis model mice." (PMID 40362650, 2025). "The association between the APOE ε4 allele and increased risk of cardiovascular diseases and atherosclerosis is well established in the literature and could be partly explained by high circulating levels of cholesterol characteristic of ε4 carriers." (PMID 40275327, 2025). "ApoE-deficient mice, widely recognized animal model of atherosclerosis, show pronounced vascular lipid deposition and inflammation, conditions known to contribute to vascular dementia and cognitive impairment, especially under high cholesterol dietary conditions." (PMID 40275327, 2025). "Furthermore, induced HHcy is known to accelerate atherosclerosis in ApoE−/− mice, which are genetically predisposed to developing this pathological condition." (PMID 40650206, 2025). "Early studies in chickens and pigs exhibited variable effects of dietary interventions on LOX activity, whereas in rabbits with advanced atherosclerosis and ApoE-deficient mice on a high-fat diet, LOX activity was elevated, and BAPN treatment ameliorated atherosclerosis." (PMID 40661776, 2025).
atherosclerosis (continued). "Thus, Apoeshl mice, which spontaneously develop symptoms, are expected to be more useful models for hyperlipidaemia, atherosclerosis, and AD than ApoE-deficient mice." (PMID 40026711, 2025). "Indeed, Id3-/-ApoE-/- mice develop significantly more atherosclerosis compared to Id3+/+ApoE-/- mice, demonstrating a direct relationship between loss of Id3 and increased atherosclerosis." (PMID 40607379, 2025). "To examine whether insulin resistance at a whole-body level leads to accelerated atherosclerosis, we generated mice with haploinsufficiency of the insulin receptor (IR+/−), deficient in Apolipoprotein E (ApoE−/−) and fed them a Western diet for 12 weeks." (PMID 39401163, 2024). "Recently, we demonstrated that activation of FFAR4 by its agonist, TUG-891, inhibited atherosclerosis in mice with knockout of apolipoprotein E (apoE−/−mice), which was associated with a beneficial phenotypical change between M1/M2 macrophages in atherosclerotic plaques." (PMID 36705799, 2024). "Researchers reported that the cross-breeding of ApoE-/- mice with mice having a heterozygous mutation (C1039G+/-) in the fibrillin-1 (Fbn1) gene revealed the effect of altered elastin structure of the arterial wall on the advancement of atherosclerosis." (PMID 38629090, 2024). "A loss of ID3 accelerates atherosclerosis development in ApoE-depleted mice fed an atherogenic diet, but here we found that the expression of genes involved in the lipid metabolism and atherosclerosis are increased after HIV infection and oxLDL treatment itself." (PMID 38397063, 2024). "Autoantibodies against apolipoprotein A-1 (AAA-1s) predict increased CVD risk, promoting atherosclerosis and liver steatosis in apoE−/− mice, though their impact on liver inflammation and fibrosis remains unclear." (PMID 39595946, 2024). "ApoE was first identified to be a major risk factor for atherosclerosis." (PMID 39169951, 2024). "Interestingly, in atherosclerosis-prone ApoE-deficient mice, FXR inactivation was shown to reduce atherosclerosis development, despite an increase in serum cholesterol and TGs." (PMID 38180064, 2024). "Similarly, the consumption of blueberries, which are rich in antioxidants, has protective effects against atherosclerosis in ApoE-deficient (ApoE−/−) mice by reducing oxidative stress." (PMID 39765884, 2024). "In the present report, we demonstrate that mice haploinsufficient for the insulin receptor, and deficient in Apolipoprotein E develop accelerated atherosclerosis, showing for the first time that insulin resistance at a whole body level drives the development of atherosclerosis." (PMID 39401163, 2024). "INCB3344 was tested in an apolipoprotein E-deficient (apoE−/−) mouse model of atherosclerosis." (PMID 39201480, 2024). "Apolipoprotein E-deficient (ApoE−/−) male mice are predisposed to atherosclerosis." (PMID 39175877, 2024). "Therefore, our objective was to evaluate the role of Cap on risk factors associated with atherosclerosis using ApoE KO mice, a model highly susceptible to atherosclerosis." (PMID 39339767, 2024). "They observed that this platform could effectively mitigate atherosclerosis in ApoE−/− (Apolipoprotein E-deficient) mice." (PMID 39543114, 2024). "However, Ascophyllum nodosum-derived fucoidan is found to inhibit the expression of PPARγ and elevate the expression of PPARα, thereby attenuating hyperlipidemia and atherosclerosis in ApoE-deficient mice." (PMID 38699583, 2024). "Importantly, adeno-associated virus mediated gene therapy to reduce LXN in ApoE-/- mice revealed that LXN deficiency improves atherosclerotic plaque formation in the mouse atherosclerosis model." (PMID 39424784, 2024).
atherosclerosis (continued). "It has been hypothesised that higher genetic liability to AD (including APOE ε4 variants) may impact AD risk via its effect on atherosclerosis." (PMID 38365930, 2024). "Similarly, heart-protecting musk pill (麝香护心丸) is found to attenuate atherosclerosis partially via activating PPARα/CPT-1α signaling pathway in ApoE-deficient mice." (PMID 38699583, 2024). "Studies in animal models suggest that combining hyperglycemia with hyperlipidemia and atherosclerosis could exacerbate age-related hearing loss in apolipoprotein E (ApoE)-deficient male mice." (PMID 38464969, 2024). "Several genetic variations are associated with increased susceptibility to carotid stenosis: for example, variants in the APOE gene (apolipoprotein E), particularly the ε4 allele, are linked to higher cholesterol levels and an increased risk of atherosclerosis, including carotid stenosis." (PMID 39199360, 2024). "It is an animal model with spontaneous atherosclerotic plaque development, and it has been shown that in ApoE/LDL receptor double knock-out mice, the progression of atherosclerosis is usually more evident than in mice deficient for ApoE alone, even on a typical chow diet." (PMID 38629090, 2024). "These APOE genotypes are associated with different risks of atherosclerosis." (PMID 37579971, 2023). "Although no definiteive evidence indicates that Akermancia directly regulates glycerophospholipid metabolism, relevant studies have reported that decreased relative abundance of Akkermansia is associated with increased content of LPC in ApoE-/- mice with atherosclerosis co-depression." (PMID 37151876, 2023). "Furthermore, the various isoforms of apoE each have different impacts on the concentration of low-density lipoprotein and the risk of atherosclerosis, thereby indicating their significant influence on cardiovascular health." (PMID 38144368, 2023). "Apolipoprotein-E-deficient (apoE−/−) mice are an extensively used model of human atherosclerosis." (PMID 37421501, 2023). "Furthermore, feeding the 1,3‐butanediol‐containing diet from early in life increases midlife mortality in normal mice, but in aged mice it extends life span and prevents the high mortality associated with atherosclerosis in ApoE‐deficient mice." (PMID 37060184, 2023). "To further investigate the effect of miR-33a deficiency on atherosclerosis, we crossed miR-33a-deficient mice with apolipoprotein E (ApoE)-deficient mice, which are used to model atherosclerosis, and fed them a diet containing 0.15% cholesterol for 16 weeks from 6 weeks of age." (PMID 37833930, 2023). "To test the hypothesis that GSDME-mediated pyroptosis aggravates the progression of atherosclerosis, we generate ApoE and GSDME dual deficiency mice." (PMID 36807553, 2023). "ApoE deficiency results in spontaneous atherosclerosis in standard rodent-chow-fed animals; these lesions occur most frequently in the proximal aorta and are characterized by vascular inflammation associated with infiltration of macrophages and other immune cells." (PMID 37628966, 2023). "We previously reported that ligature-induced periodontitis exacerbates atherosclerosis in Apolipoprotein E (ApoE)-deficient mice and also found that hyperlipidemia is required for the development and progression of atherosclerosis in mice with ligature-induced periodontitis." (PMID 37628753, 2023). "Therefore, PACAP has been suggested to act as an endogenous athero-protective neuropeptide, whereas PAC1 deficiency attenuates the progression of atherosclerosis in ApoE−/− mice." (PMID 37980508, 2023). "Moreover, in the process of atherogenesis, the ability of macrophages to synthesize glutathione is inversely related to the initiation and progression of atherosclerosis in apolipoprotein E deficient mice (Apo E-/-)." (PMID 37107209, 2023). "Studies have examined how APOE-driven hyperlipidemia modulates susceptibility to atherosclerosis." (PMID 38034385, 2023).
atherosclerosis (continued). "It is reported that LYPLA3′s loss increased atherosclerosis in apolipoprotein E-deficient mice." (PMID 37510289, 2023). "Thus, ApoE deficiency-driven spontaneous atherosclerosis was examined in standard rodent-chow-fed TG/ApoE−/− mice." (PMID 37628966, 2023). "A similar regulation of Dnm3os was observed in macrophages from high-fat diet-induced insulin-resistant mice, streptozotocin (STZ)-induced type 1 diabetic mice, and STZ-induced diabetic apolipoprotein E deficient mice (a model of accelerated atherosclerosis) compared with controls." (PMID 37226245, 2023). "The current GA intervention dosage and duration may be insufficient to counter UA-associated hyperlipidemia, as observed in atherosclerosis-prone apolipoprotein E knockout mice fed a high-fat Western-type diet." (PMID 37993853, 2023). "To determine the causative effect of caspase-1 in HIV-1-associated atherosclerosis, we compared the development of atherosclerosis in caspase-1-sufficient vs. -deficient mice carrying the HIV transgene with an atherogenic background (Tg26+/−/ApoE−/−/Casp-1+/+ vs. Tg26+/−/ApoE−/−/Casp-1−/−)." (PMID 37629052, 2023). "Recent evidence shows PACAP deficiency aggravates atherosclerosis in ApoE−/− mice." (PMID 37980508, 2023). "Additionally, intravenous administration of adenovirus-mediated expression of PAF-AH in ApoE–deficient mice inhibited atherosclerosis by reducing oxidized lipoprotein accumulation." (PMID 37189447, 2023). "Although APOE alleles are related to lipid metabolism, atherosclerosis, inflammation processes, and oxidative stress, prior studies have not found mediation effects of cerebrovascular lesions on the relationship of APOE alleles with cognition, which is in line with our results." (PMID 38115150, 2023). "Therefore, to evaluate the role of naturally occurring ILC2s in atherosclerosis, another group made use of an apolipoprotein e-deficient (Apoe-/-) mouse model that is susceptible for atherosclerosis development." (PMID 38179045, 2023). "CAD risk variants located at the JCAD (junctional cadherin 5 associated, also known as KIAA1462) locus were associated with increased gene expression in human arteries and JCAD knockout reduced the development of atherosclerosis in apolipoprotein E-deficient (ApoE−/−) mice." (PMID 37759455, 2023). "A previous study demonstrated acceleration of atherosclerosis following stroke in ApoE deficient mice suggesting common proatherogenic pathways may be activated following acute cerebrovascular events." (PMID 37235594, 2023). "Perhexiline regulates the KLF14 pathway, and the results revealed that this intervention diminishes the development of atherosclerotic lesions in the apolipoprotein E-deficient mice which have a high cholesterol level and more chances for the development of atherosclerosis." (PMID 36837818, 2023). "A meta-analysis published in 2016 evaluated the association of polymorphisms of the APOE gene with susceptibility to atherosclerosis; a subgroup examination based on clinical phenotypes showed that ε4 carriers were prone to develop major clinical manifestations related to atherosclerosis." (PMID 37629219, 2023). "ApoE-deficient mice develop lesions of severe hypercholesterolemia and atherosclerosis, which may resemble those in humans." (PMID 37396111, 2023). "The single lead variant associated with Lewy body dementia (19_44908684_T_C, rs429358) is part of cluster 21 that is linked to APOE and involves 9 age-related traits including age-related macular degeneration, Alzheimer’s disease, atherosclerosis, as well as longevity." (PMID 37749083, 2023). "The miR-103 was shown to be highly expressed in ApoE-/- mice and linked with atherosclerosis." (PMID 36768651, 2023). "However, the APOE alleles are also associated with a higher risk of cerebrovascular lesions, including atherosclerosis, brain infarcts, hyaline arteriosclerosis, and cerebral amyloid angiopathy (CAA)." (PMID 38115150, 2023).
atherosclerosis (continued). "Given the causal role of systemic metabolic disorders in atherosclerosis, we next explored whether swim training alleviated atherosclerosis in an EV dependent manner in ApoE-/- mice." (PMID 37191422, 2023). "Several observations documented so far relate, for example, to the correlation between increased DNMT1 in macrophages and decreased PPAR-γ and increased pro-inflammatory cytokines in apolipoprotein E (ApoE)-deficient mice fed an atherogenic diet as well as in patients with atherosclerosis." (PMID 37762023, 2023). "However, as hyperlipidemia is necessary to evaluate the degree of arterial lipid deposition, we used ApoE-deficient mice to assess the effect of GV1001 on arterial lipid accumulation/atherosclerosis." (PMID 37628753, 2023). "We also observed that C8:0 could reduce TC and LDL-C levels, increase the HDL-C/LDL-C ratio, and improve atherosclerosis in apoE-deficient mice." (PMID 36904298, 2023). "Moreover in humans, the homozygous APOE deficiency has been associated with severe atherosclerosis and premature CVD." (PMID 37579971, 2023). "The therapeutic potential for improving the lesion stability by targeting CD36 with the cyclic azapeptide MPE-298 has now been investigated in a preclinical mouse model of atherosclerosis featuring apolipoprotein E-deficient (apoE−/−) mice fed a high-fat high-cholesterol (HFHC) diet." (PMID 37332345, 2023). "Animal model of atherosclerosis: apoE-deficient mice fed with a high-cholesterol diet." (PMID 37510734, 2023). "It had been demonstrated that ApoE deficiency could lead to the accumulation of cholesterol-rich remnants in plasma and then induce atherosclerosis." (PMID 35845572, 2022). "ApoE-deficient mice are widely used to study the factors involved in atherosclerosis." (PMID 35456980, 2022). "Therefore, the APOE ε2 allele has both increased and decreased risks for atherosclerosis, which induced a comprehensive and undetermined result." (PMID 35154509, 2022). "Ang II- and high salt-induced hypertension facilitated the development of atherogenesis in apolipoprotein E-deficient mice (ApoE KO) whereas Ang II-induced atherosclerosis was attenuated by enalapril treatment in vivo because of its anti-atherogenic and anti-inflammatory effects." (PMID 36359240, 2022). "Recent studies have shown that NOX4 may prevent the development of atherosclerosis and endothelial dysfunction in apolipoprotein E–deficient (apoE–/–) mice." (PMID 35617030, 2022). "Studies from our group and others have demonstrated that astragalin, C1q tumor necrosis factor-related protein 12, fargesin and biochanin A increase RCT efficiency and protect against atherosclerosis in apolipoprotein E-deficient (apoE−/−) mice by up-regulating ABCA1 and ABCG1 expression." (PMID 35902881, 2022). "The Apolipoprotein E2 (APOE2) knock-in (APOE2ki) mouse model was generated when the murine Apoe gene was replaced by a human Apolipoprotein E2 (APOE*2) gene allele via targeted gene replacement in embryonic stem cells and was first used as a model for hyperlipoproteinemia and atherosclerosis." (PMID 36555433, 2022). "Finally, we further studied the relationship between the changes of the gut microbiota and the lipid metabolisms phenotype of brain areas in ApoE−/− mice with atherosclerosis co-depression by the association analysis." (PMID 35558553, 2022). "Additionally, histone deacetylase 3 (HDAC3) has been reported as having a protective effect in apolipoprotein E deficient (ApoE−/−) mice as it maintains the endothelial integrity and its deficiency results in atherosclerosis." (PMID 35563540, 2022). "Furthermore, PLT3 was much more effective than systemic T3 therapy in reducing hypercholesterolemia and atherosclerosis in apoE-deficient mice." (PMID 36539421, 2022).